CHN2 (chimerin 2)
Description:
GTPase-activating protein for p21-rac. Insufficient expression of beta-2 chimaerin is expected to lead to higher Rac activity and could therefore play a role in the progression from low-grade to high-grade tumors.
Synonyms: ARHGAP3; BCH; RhoGAP3; CHN2-3
Tractability: Antibody: UniProt places it where antibodies can reach, with high confidence. PROTAC: ubiquitination databases record sites on it; its protein half-life has been measured; a small molecule that binds it is known.
Target class: Other cytosolic protein
Gene: Protein-coding gene on chromosome 7 (29,146,547 to 29,514,334, forward strand). Ensembl gene ENSG00000106069.
Subcellular location: Membrane
Subcellular location (Human Protein Atlas): Nucleoplasm; Nuclear bodies
Pathways (Reactome):
Signal Transduction: RAC1 GTPase cycle
Gene Ontology:
Molecular function: GTPase activator activity; protein binding
Biological process: acrosome assembly; regulation of small GTPase mediated signal transduction; signal transduction
Cellular component: synapse; cytosol; membrane
Genetic constraint (gnomAD): Loss-of-function variants: 27 observed, 42.07 expected, observed/expected ratio (o/e) 0.64, 90% interval 0.47 to 0.88. The upper end of that interval is the gene's LOEUF score, 0.88, which puts it in group 3 of 6, group 1 being the genes least tolerant of losing a copy. Missense variants: 469 observed, 564.54 expected, observed/expected ratio (o/e) 0.83, 90% interval 0.77 to 0.9. Synonymous variants: 199 observed, 214.19 expected, observed/expected ratio (o/e) 0.93, 90% interval 0.83 to 1.04.
Homologues: Orthologues: chimpanzee CHN2 (100% identical), macaque CHN2 (99% identical), guinea pig CHN2 (99% identical), mouse Chn2 (98% identical), dog CHN2 (97% identical), tropical clawed frog chn2 (84% identical), zebrafish chn2 (81% identical), pig CHN2 (58% identical), rat Chn2 (58% identical), rabbit CHN2 (58% identical), Caenorhabditis elegans chin-1 (35% identical), Drosophila melanogaster RhoGAP5A (17% identical). Paralogues in human: CHN1 (72% identical), SYDE2 (25% identical), ARHGAP35 (23% identical), SYDE1 (21% identical).
Diseases named in the same sentence as CHN2 in open-access papers:
CHN2 is named in the same sentence as 30 diseases in open-access papers, as found by Europe PMC text mining. Sharing a sentence is not in itself a finding about the gene and the disease. The quoted sentences say what the papers report.
diabetes (4 papers, 2017 to 2024). "Further supporting the role of β2-chimaerin in glucose metabolism, polymorphisms in the CHN2 gene have been associated with the development of diabetes and its complications." (PMID 39598690, 2024). "Previous studies reported associations between the CHN2 gene and insulin-resistance, diabetes, and obesity phenotypes as well as with addiction and neurological diseases." (PMID 31766143, 2019). "Haploinsufficiency of the gene encoding for β2-chimaerin (CHN2) in combination with the insulin receptor gene (INSR) was detected in a family with insulin resistance and early diabetes onset, being one of the few examples of the digenic cause of disease in diabetic patients." (PMID 39598690, 2024). "Furthermore, eight of the 17 CpG sites reside in genes (FSTL1, SORCS2, NRF1, DLC1, PPARGC1B, CHN2, NXPH1) that have prior known associations with obesity, diabetes, and the insulin pathway." (PMID 28068899, 2017).
breast carcinoma (3 papers, 2012 to 2022). "Deregulation of the CHN2 gene has been associated with human pathologies including mental disorders, insulin resistance, and cancers such as glioblastoma, hepatosplenic T-cell lymphoma and breast cancer." (PMID 27058424, 2016). "We found that low CHN2 expression levels in unstratified breast cancer patients significantly correlated with reduced relapse-free survival (P < 0.001)." (PMID 27058424, 2016). "Similar to CHN2 and RGS2, we predict that a significant number of genes upregulated in ERBB2 overexpressing luminal breast cancers are indeed PR-driven." (PMID 22697792, 2012).
Cerebral ischemia (2 papers, 2023 to 2025). Restriction of arterial blood supply to the brain associated with insufficient oxygenation to support the metabolic requirements of the tissue. "ChN2 demonstrated strong neuroprotective and antioxidant effects in both in vitro and in vivo models of cerebral ischemia." (PMID 41373660, 2025).
schizophrenia (2 papers, 2006 to 2017). A major psychotic disorder characterized by abnormalities in the perception or expression of reality. "Indeed, there are several other genes (e.g., ZDHHC8 and chimerin 2) that have been suggested to have a sexually dimorphic effect on the development of schizophrenia." (PMID 17134514, 2006).
viral disease (2 papers, 2021 to 2023). "The TOA assay showed that Z-Tyr-Ala-CHN2 antiviral activity was lost when administered at 2 h post virus infection or later, suggesting that the compound targets one of the early steps in the SARS-CoV-2 replication cycle." (PMID 36985290, 2023). "YLD is a very common viral disease, and at least six SCYLV genotypes (BRA, CHN1, CHN2, CHN3, CUB, and PER or HAW) occurr in China28,30,31,35." (PMID 33785787, 2021).
AIDS (1 paper, 2022). A syndrome resulting from the acquired deficiency of cellular immunity caused by the human immunodeficiency virus (HIV). "Five genotypes of E. bieneusi were found among all the HIV/AIDS patients studied, including two known genotypes (D and EbpC) and three novel genotypes (CHN-H1, CHN2, and CHN-H3)." (PMID 36067140, 2022).
Alzheimer disease (1 paper, 2024). A progressive, neurodegenerative disease characterized by loss of function and death of nerve cells in several areas of the brain leading to loss of cognitive function such as memory and language.
breast tumors (1 paper, 2016). "Additionally, we examined the prognostic value of CHN2 expression in a large clinical microarray database of human breast tumors." (PMID 27058424, 2016).
chordoma (1 paper, 2008). Chordomas are rare malignant tumors arising from embryonic remnants of the notochord in axial skeleton. "This region harbours the genes CREB5, CPVL, and CHN2, none of which has any obvious role in chordoma development." (PMID 18071362, 2008).
colon cancer (1 paper, 2025). "This analysis revealed that low CHN2 expression in unstratified colon cancer patients significantly correlated with reduced overall survival (p < 0.001), relapse-free survival (p < 0.001), and post-progression survival (p < 0.05)." (PMID 40005135, 2025). "To assess the relevance of our experimental findings in human colon cancer, we evaluated the prognostic value of the β2-chimaerin gene (CHN2) expression using a large clinical microarray database of colon cancer patients via the Kaplan–Meier plotter tool." (PMID 40005135, 2025).
diabetic retinopathy (1 paper, 2015). "Several identified genes with altered DNA methylation in cases with PDR, such as TNF, CHI3L1, and CHN2, encode proteins with previous known function in diabetic complications and/or diabetic retinopathy." (PMID 26248552, 2015). "Interestingly, a SNP in an intron of CHN2 was recently associated with diabetic retinopathy in Chinese people with T2D, further supporting a role for this gene in the development of diabetic retinopathy." (PMID 26248552, 2015).
ischemia (1 paper, 2023). A hypoperfusion of the BLOOD through an organ or tissue caused by a PATHOLOGIC CONSTRICTION or obstruction of its BLOOD VESSELS, or an absence of BLOOD CIRCULATION. "ChN2 also exhibited a notable potency in the ischemia model (EC50 = 0.66 ± 0.23 μM), while QN23 (EC50 = 2.13 ± 0.47 μM) displayed a slightly higher EC50 value, although it was significantly lower than that of PBN (EC50 = 8.24 ± 1.49 μM)." (PMID 37507904, 2023).
ischemic stroke (1 paper, 2023). A stroke disorder caused by obstruction of blood flow to the brain, due to thrombotic (local blood clot formation) or embolic (due to a blood clot or other material traveling from another site) event. "Here, we conducted a comprehensive examination of the neuroprotective profiles of ChN2 and QN23, two synthetic nitrones that have demonstrated considerable potential for the treatment of ischemic stroke in previous in vitro and in vivo studies conducted by our research group." (PMID 37507904, 2023).
mental disorder (1 paper, 2024). A disease that has its basis in the disruption of mental process. "CHN2 deregulation has been linked to mental disorders and cancers." (PMID 39639867, 2024).
Stroke (1 paper, 2023). Sudden impairment of blood flow to a part of the brain due to occlusion or rupture of an artery to the brain. "In this study, we aimed to further investigate the neuroprotective effects of two nitrones, cholesteronitrone 2 (ChN2) and quinolylnitrone 23 (QN23), which have previously shown great potential for the treatment of stroke." (PMID 37507904, 2023).
tumor (3 papers, 2015 to 2024). "As this trend was observed in all normal-tumor pairs, CHN2 methylation has potential to act as a biomarker for SBA screening in blood/stool samples." (PMID 26315110, 2015). "The Adgrg1, Pdcd1, Osgin1, Lag3, and Chn2 were predominantly expressed in tumor-reactive T cells." (PMID 39243082, 2024). "The top 10 downregulated genes are involved in different signalling pathways, such as the CHN2 gene in the regulation of RAC1 activity, the FOS gene in EGFR signalling and ITGA7 in integrin pathways and Akt signalling and in tumour initiation and progression." (PMID 32613561, 2020).
infection (1 paper, 2017). The state of being infected such as from the introduction of a foreign agent such as serum, vaccine, antigenic substance or organism. "In contrast, expression of genes for PR-1, PR-10, three chitinases, and a glucan endo-1,3-beta-glucosidase 7 significantly decreased after infection with A. flavus, and expression of chitinase 2 (chn2) decreased in F. verticillioides infected kernels." (PMID 29270183, 2017).
CHN2 also shares sentences with these, for which no sentence is quoted: Obesity (4 papers); Insulin resistance (3); Roussy-Levy syndrome (2); amyotrophic lateral sclerosis (1); atherosclerosis (1); cancer (1); diabetic nephropathy (1); growth deficiency (1); Hyperglycemia (1); methamphetamine dependence (1); neurological diseases (1); Parkinson disease (1); type 2 diabetes (1).